KISS1R (KISS1 receptor)
Description:
Receptor for kisspeptins (kisspeptin-10, kisspeptin-13, kisspeptin-14 and metastin/kisspeptin-54). The hypothalamic KISS1/KISS1R signaling system plays a central role in the regulation of the hypothalamic-pituitary-gonadal reproductive axis by modulating the secretion of gonadotropin-releasing hormone (GnRH) from GnRH neurons. In these neurons, kisspeptin binding to its receptor activates G(q)-dependent signaling, leading to phospholipase C (PLC) activation, and hydrolysis of phosphatidylinositol 4,5-bisphosphate (PIP2). The subsequent rise in intracellular calcium levels results in the inhibition of inward rectifier potassium channels and activation of TRPC-like cation channels, leading to GnRH neurons depolarization and stimulation (By similarity). In addition to this pathway, kisspeptin also triggers G(q)-independent signaling via beta-arrestin, leading to MAPK cascade activation and ERK1/ERK2 phosphorylation. Furthermore, activation of KISS1R by kisspeptin-10 recruits phosphatase DUSP18 and SRC to the KISS1R C-terminus through a G(q)-dependent signaling pathway, leading to DUSP18-mediated dephosphorylation of SRC. In bone tissue, this results in down-regulation of osteoclast differentiation and activity, and consequently suppression of bone resorption (By similarity). KISS1R is also involved in the regulation of other processes, including cell proliferation and cell migration.
Synonyms: KiSS-1R; hOT7T175; AXOR12; GPR54; CPPB1; HH8
Tractability: Small molecule: a high-quality ligand is known; it belongs to a druggable protein family. Antibody: its Gene Ontology location is reachable by antibodies, with high confidence; UniProt places it where antibodies can reach, with medium confidence; UniProt predicts a signal peptide or a membrane-spanning region; the Human Protein Atlas places it where antibodies can reach. PROTAC: a small molecule that binds it is known.
Target class: Membrane receptor; RF amide receptor; Family A G protein-coupled receptor; Peptide receptor (family A GPCR); Short peptide receptor (family A GPCR)
Chemical probes: KISS1-305 (high quality)
Gene: Protein-coding gene on chromosome 19 (917,287 to 921,005, forward strand). Ensembl gene ENSG00000116014.
Subcellular location: Cell membrane
Subcellular location (Human Protein Atlas): Plasma membrane; Vesicles
Pathways (Reactome):
Signal Transduction: G alpha (q) signalling events; Peptide ligand-binding receptors
Gene Ontology:
Molecular function: G protein-coupled receptor activity; neuropeptide receptor activity; protein binding; G protein-coupled peptide receptor activity; molecular adaptor activity
Biological process: phospholipase C-activating G protein-coupled receptor signaling pathway; positive regulation of gonadotropin secretion; G protein-coupled receptor signaling pathway; negative regulation of bone resorption; negative regulation of osteoclast differentiation; neuropeptide signaling pathway; positive regulation of hormone secretion; positive regulation of membrane depolarization; regulation of membrane depolarization; regulation of monoatomic cation transmembrane transport; regulation of transport
Cellular component: cilium; membrane; plasma membrane; cell surface
Genetic constraint (gnomAD): Loss-of-function variants: 21 observed, 14.65 expected, observed/expected ratio (o/e) 1.43, 90% interval 1.01 to 1.89. The synonymous counts are far from expectation, so gnomAD's model fits this gene poorly and the ratio says little. Missense variants: 653 observed, 425.78 expected, observed/expected ratio (o/e) 1.53, 90% interval 1.44 to 1.64. Synonymous variants: 302 observed, 201.21 expected, observed/expected ratio (o/e) 1.5, 90% interval 1.37 to 1.65.
Homologues: Orthologues: chimpanzee KISS1R (97% identical), macaque KISS1R (97% identical), pig KISS1R (86% identical), rat Kiss1r (83% identical), mouse Kiss1r (82% identical), tropical clawed frog kissr1b (50% identical), zebrafish kiss1rb (44% identical), Drosophila melanogaster AstC-R1 (25% identical), Caenorhabditis elegans npr-24 (20% identical), Caenorhabditis elegans npr-16 (18% identical), Caenorhabditis elegans npr-32 (18% identical). Paralogues in human: SSTR3 (28% identical), OPRD1 (28% identical), SSTR5 (28% identical), OPRL1 (28% identical), SSTR4 (26% identical), OPRK1 (25% identical), SSTR1 (25% identical), NPBWR1 (25% identical), OPRM1 (25% identical), NPBWR2 (24% identical), SSTR2 (24% identical), UTS2R (20% identical), and 5 more.
Diseases named in the same sentence as KISS1R in open-access papers:
KISS1R is named in the same sentence as 124 diseases in open-access papers, as found by Europe PMC text mining. Sharing a sentence is not in itself a finding about the gene and the disease. The quoted sentences say what the papers report.
hypogonadotropic hypogonadism (53 papers, 2009 to 2025). Abnormal ovarian or testicular function due to insufficient hormonal stimulation from the hypothalamic-pituitary axis. "KISS1 gene mutations and subsequent KISS1/KISS1R system dysregulation can lead to a range of idiopathic clinical symptoms, such as hypogonadotropic hypogonadism, central precocious puberty, and female infertility." (PMID 39558653, 2024). "Functional genomic studies documented that kisspeptin actions on GnRH neurons suffice for attainment of reproductive capacity, while elimination of Kiss1r selectively from GnRH cells caused central hypogonadism." (PMID 38861336, 2024). "In humans, mutations in the gene that encodes KISS1R lead to deficiency in the production of gonadotropin-releasing hormone (GnRH), which culminates in hypogonadotropic hypogonadism." (PMID 38606141, 2024). "Two groups almost simultaneously identified an autosomal recessive cause of hypogonadotrophic hypogonadism in consanguineous families, caused by inactivating variants in KISS1R." (PMID 36479214, 2022). "Homogeneous mutation of either KISS1 or KISS1R is associated with hypogonadotropic hypogonadism and infertility." (PMID 35606759, 2022). "Inactivating variants of the gene encoding KP (KISS1) or its receptor KISS1R (KISS1R) result in congenital hypogonadotrophic hypogonadism and a failure to proceed through puberty in humans and murine models." (PMID 36479214, 2022). "Humans with inactivating mutations of KISS1 or KISS1R display a phenotype of hypogonadotropic hypogonadism, whereas activating mutations of KISS1 or KISS1R causes central precocious puberty." (PMID 35757400, 2022). "Mutations in the KISS1 gene or KISS1R can lead to idiopathic hypogonadotropic hypogonadism and delay pubertal maturation of the gonadotropic axis, suggesting that KISS1R is indispensable for normal GnRH secretion." (PMID 35606759, 2022). "The kisspeptin/KISS1R system has been established as a regulator of puberty based on studies showing that inactivating and activating mutations in either KISS1 or KISS1R were associated with hypogonadotropic hypogonadism and precocious puberty." (PMID 36457308, 2022). "Males with the deletion or mutation in the KISS1 receptor gene are shown to develop hypogonadotropic hypogonadism." (PMID 34646652, 2021). "Mutations in the KISS1R gene (gene ID: 9291), located at 19p13.3, were associated with hypogonadotropic hypogonadism in humans, which suggests that kisspeptin and its receptor play an important part in the regulation of the HPG axis." (PMID 34646652, 2021). "Hypogonadotropic hypogonadism due to impaired GnRH release has been related to loss-of-function mutations of KISS1R (already known as GPR54)." (PMID 32318025, 2020). "Mutation in the KP receptor (KISS1R /GPR54) leads to hypogonadotropic hypogonadism and infertility in humans." (PMID 32210912, 2020). "Several loss-of-function mutations in KISS1R were described in patients with congenital isolated hypogonadotropic hypogonadism." (PMID 30838190, 2019). "Using complementary genetic approaches, KISS1R has been identified as the causative gene responsible for the consanguineous families with idiopathic hypogonadotropic hypogonadism." (PMID 29354093, 2017). "Mutations of KISS1R are associated with hypogonadotrophic hypogonadism in humans, a phenotype which is also observed in mice carrying inactivating mutations of KISS1 or KISS1R genes." (PMID 23915023, 2013). "Humans with mutations in KISS1R develop hypogonadotropic hypogonadism, characterised by decreased levels of sex steroids and delayed puberty." (PMID 22132116, 2011). "This system was linked to the function of the HPG axis after it was noticed that mutations in the Kiss1r gene result in hypogonadotrophic hypogonadism, and that Kiss1r knockout mice exhibit the same disorder." (PMID 19500221, 2009).
hypogonadotropic hypogonadism (continued). "Notably, loss or gain of function mutations in either Kiss1 or Kiss1 receptor (Kiss1R) genes respectively cause hypogonadotropic hypogonadism or precocious puberty in mice and humans." (PMID 33573212, 2021). "In fact, humans with mutations in the KISS1R gene, or mice with mutations in KISS1 or KISS1R genes, are affected by hypogonadotropic hypogonadism, characterized by deficient production of gonadotropins and sex steroids, which leads to an incomplete sexual maturation." (PMID 31906206, 2019). "Notably, in humans and mice, inactivating mutations in either kisspeptin or KISS1R lead to the phenotype of hypogonadotropic hypogonadism." (PMID 29354093, 2017). "Most recently, after the discovery of inactivating mutations in the kisspeptin receptor (Kiss1R) in patients with hypogonadotropic hypogonadism, it was revealed that hypothalamic kisspeptin is a stimulator of GnRH and is positioned upstream of GnRH in the HPG axis." (PMID 27681724, 2016). "KISS1R (GPR54) mutations have been reported in several patients with congenital normosmic idiopathic hypogonadotropic hypogonadism (nIHH)." (PMID 31885997, 2019). "Inactivating mutations in the KISS1R (GPR54) gene cause autosomal recessive normosmic idiopathic hypogonadotropic hypogonadism (nIHH)." (PMID 21939553, 2011). "Mutations in KISS1 or its receptor, KISS1R (also known as GPR54), can lead to hypogonadotropic hypogonadism." (PMID 41200545, 2025). "Although we identified rare or novel missense variants in several hypogonadotropic hypogonadism genes (e.g. FGF17, HS6ST1, KISS1R, CHD7, IL17RD) definitively linking them to the PSIS phenotype is premature." (PMID 38096238, 2023). "Inactivating mutations of KISS1R, which encodes the KiSS-1 receptor or KISS1 itself, cause hypogonadotropic hypogonadism in humans." (PMID 36093104, 2022). "Inactivating mutations of the genes encoding for KP (KISS1) or its G-protein-coupled receptor (KISS1R; previously called GPR-54) cause hypogonadotropic hypogonadism in humans." (PMID 25713511, 2015). "In humans, mutations of the KISS1 receptor (GPR54, more recently termed KISS1R) and a recently described inactivating KISS1 mutation lead to hypogonadotropic hypogonadism." (PMID 25093675, 2014). "Inactivating mutations of the Kp-10 receptor (Kiss1R, also known as GPR54) in humans are associated with failure to progress through puberty and adult infertility (hypogonadotropic hypogonadism)." (PMID 21347414, 2011). "These phenotypic features are different from those of global Kiss1r-KO mice, which suffer from severe central hypogonadism, or mice with conditional inactivation of Kiss1r in GnRH neurons, which phenocopy global Kissr1-KO mice, or in POMC neurons, which are devoid of a detectable phenotype." (PMID 38861336, 2024). "Hypothalamic KISS1 and KISS1R expressions decrease in many pathological conditions, resulting in the delay or absence of puberty in children, hypogonadotropic hypogonadism, and reproductive disorders." (PMID 39404414, 2024). "The importance of KISS1 in reproduction cannot be understated as whole-body knockouts of KISS1 or its receptor, GPR54/KISS1r, lead to hypogonadotropic hypogonadism, a condition where little to no sex hormones are produced, resulting in infertility and the loss of puberty." (PMID 34831343, 2021).
Infertility (34 papers, 2009 to 2025). "Then in this study, we discovered and clarified genetic mutations of KISS1R gene in a population of infertile men with NOA." (PMID 31821609, 2020). "Inactivating mutations in Kiss1 and the kisspeptin receptor (GPR54/Kiss1r) are associated with pubertal failure and infertility." (PMID 25093675, 2014). "Currently, researchers are investigating both agonists and antagonists of KISS1R as potential treatments for reproductive disorders, such as infertility, hypogonadism, and PCOS." (PMID 40430029, 2025). "The role of KISS1 in reproduction can be traced to the hypothalamus as the conditional knockout of KISS1r in GnRH neurons or KISS1 in hypothalamic neurons is enough to induce an infertile phenotype." (PMID 34831343, 2021). "The involvement of kisspeptin/KISS1R system and its downstream signaling pathways in a range of ovarian function has led researchers to develop potential therapeutic approaches to overcome ovarian pathology and infertility." (PMID 29354093, 2017). "Firstly, loss-of-function mutations in kisspeptin (Kiss1) or kisspeptin receptor (Kiss1R) genes cause infertility due to lack of pubertal maturation and hypogonadotropic hypogonadism in both mice and humans." (PMID 27990162, 2016). "Mutations in KISS1/KISS1R cause congenital GnRH deficiency (characterized by delayed or absent puberty and infertility) or central precocious puberty, and aberrant kisspeptin signaling has been implicated in polycystic ovary syndrome (PCOS) and hypothalamic amenorrhea." (PMID 40430029, 2025). "Therefore, infertility occurs in both genders due to altered GPR54/KISS1R." (PMID 34646652, 2021). "In this study, the GnRH1, GnRHR, KISS1, KISS1R, TAC3 and TAC3R genes were analyzed in two unrelated nIHH patients successfully treated for infertility." (PMID 27544332, 2016). "Two studies have recently shown that kisspeptin signaling through Kiss1r on the GnRH neuron is essential for reproductive function; GnRH neuron-specific deletion of the Kiss1r resulted in absent puberty over the 6-month experimental period, no estrous cyclicity, and infertility." (PMID 25875299, 2015).
breast carcinoma (28 papers, 2007 to 2025). "Since KISS1R signaling is now implicated in the promotion of metastasis and drug resistance, two major factors leading to poor breast cancer patient prognosis, it may be an attractive drug target for the development of therapeutics to improve treatment of TNBC patients." (PMID 28422142, 2017). "Complementing these in vitro observations, heterozygous Kiss1r+/− mice in a breast cancer model exhibited reduced breast tumor initiation and lung metastasis." (PMID 40430029, 2025). "Further studies revealed that the suppression of KISS1/KISS1R signaling allows for the progression and metastasis of osteosarcoma, gastric, prostate, and breast cancer." (PMID 40430029, 2025). "There is a lot of evidence that the KP/KISS1R system positively correlates with tumor invasiveness and poor prognosis in most breast cancers." (PMID 38256878, 2023). "Activation of the kisspeptin receptor KISS1R by the peptide hormone kisspeptin-10 (KP-10) stimulates invasion of breast carcinoma cells via transactivation of EGFR." (PMID 37071417, 2023). "While it seems clear that kisspeptin and its receptor KISS1R play a role in preventing or inhibiting metastasis in a number of cancer types, controversy remains regarding its role in breast cancer." (PMID 35955878, 2022). "Previous studies have shown that KISS1 and KISS1R can suppress metastasis of numerous cancers, such as breast carcinoma, nasopharyngeal carcinom, bladder and ovarian cancer." (PMID 35117986, 2021). "The role of KISS1/KISS1R signaling is yet unclear in cancer, though it has been proposed to suppress cancer metastasis, such as melanoma, gastric cancer, breast cancer and pancreatic." (PMID 35117986, 2021). "Our future studies will examine the clinical relevance of KP/KISS1R signaling in other breast cancer subtypes, which have a distinct molecular characteristics and clinical regiments, compared with TNBC1,53." (PMID 32034133, 2020). "In support of our findings, mouse Kiss1r has been shown to stimulate breast cancer metastasis in a mouse mammary tumor virus–polyoma virus middle T antigen model." (PMID 30046386, 2018). "We show that Star-PAP and PIPKIα together regulate 3′-end processing and expression of pre-mRNAs encoding key anti-invasive factors (KISS1R, CDH1, NME1, CDH13, FEZ1, and WIF1) in breast cancer." (PMID 29203642, 2018). "Taken together, these in vitro, animal model studies and clinical findings provide substantial support that KISS1 and KISS1R promote metastasis in breast cancer." (PMID 30123188, 2018). "Spanning a little over one decade, several studies have highlighted a detrimental role for KISS1/KISS1R in breast cancer." (PMID 30123188, 2018). "Taken together, these results indicate that KISS1R signaling in breast cancer promotes doxorubicin resistance by upregulating BCRP expression, leading to reduced intracellular drug accumulation and reduced cytotoxicity." (PMID 28422142, 2017). "More recently, in a mouse mammary tumor virus model, Kiss1r has been shown to stimulate breast cancer metastasis." (PMID 28422142, 2017). "KISS1R, which is also on the gene signature list, is a predictive marker for pancreatic cancer, lung cancer, breast cancer, renal cell carcinomas." (PMID 28404969, 2017). "While KISS1 is noted as a tumor suppressor in melanoma metastasis, the role of KISS1R signaling on breast cancer invasion is dependent on the estrogen receptor status of the tumor cells." (PMID 27158817, 2016). "KISS1R expressed in skeletal precursor cells was also found to be of a greater molecular weight than that expressed in the MM cell line INA-6, as well as in the breast cancer cell line MCF-7 previously characterized to express high levels of the KISS1R." (PMID 27158817, 2016). "Kisspeptin/KISS1R interactions and activation of the Gqα–p63RhoGEF signaling cascade has been identified as a driver of metastasis in breast cancer cells." (PMID 27015368, 2016).